FMR1 (fragile X messenger ribonucleoprotein 1)
Diseases named in the same sentence as FMR1 in open-access papers (continued):
Sharing a sentence is not in itself a finding about the gene and the disease.
fragile X syndrome (continued). "The Fmr1 knock-out mouse (Fmr1-KO) is an example of this approach: it is a confirmed model of Fragile X syndrome (FXS), a genetic disorder due to a mutation in the FMR1 gene leading to a lack of FMRP, a protein playing a pivotal role in synaptic functioning." (PMID 21364941, 2011). "Expansions of a CGG repeat tract in the 5'UTR region of the FMR1 gene causes the fragile X syndrome (FXS), the most common inherited cause of mental retardation." (PMID 21639881, 2011). "Fragile X Syndrome (FXS) is an inherited cause of intellectual disability and autism, arising from silencing of the Fmr1 gene and loss of Fragile X Messenger Ribonucleoprotein 1 (FMRP)." (PMID 42196339, 2026). "A mouse model of fragile X syndrome, the Fmr1 knock-out (KO) mouse, has been particularly valuable for interrogating the molecular, cellular, and circuit mechanisms that underlie the neurological deficits seen in this syndrome." (PMID 41922168, 2026). "A full mutation of FMR1 (>200 CGG repeats) results in transcriptional silencing of FMR1 and loss or reduction in FMRP expression, which results in fragile X syndrome (FXS)." (PMID 40141125, 2025). "In fact, hyperactivation of mitochondrial respiration complexes has been previously reported in the striatum of a Fmr1-knockout mouse model of the neurodevelopmental disorder Fragile X syndrome." (PMID 41022686, 2025). "The yellow cluster mainly described fragile X syndrome, containing “disorder”, “FMR1” “premutation”, and “CGG repeat” as keywords." (PMID 38919087, 2025). "In Fmr1 KO mice, a model of Fragile X Syndrome, selective 5-HT7 receptor agonists rescued synaptic plasticity, memory and stereotyped behavior." (PMID 40141138, 2025). "Results will be presented from the initial pilot studies on newborn blood spots of 16,579 infants, focusing on 1st tier newborn screening for fragile X syndrome and confirmatory 2nd tier testing using FMR1 CGG sizing and methylation analyses." (PMID 40275386, 2025). "This is particularly prominent in fragile X syndrome (FXS), which is caused by an expansion of a CGG repeat tract in the FMR1 gene, which was discovered by Warren and colleagues." (PMID 40149430, 2025). "ECT appears to be well tolerated and effective in Fragile X syndrome or premutation careers – the FMR1 expansion results in reduced levels of Fragile X mental retardation protein (FMRP)." (PMID 40400398, 2025). "Supplying the functional protein product of the FMR1 gene to the brain is an attractive concept for curative treatment of Fragile X syndrome." (PMID 41207793, 2025). "The neurodevelopmental disorder Fragile X syndrome (FXS) results from hypermethylation of the FMR1 gene which prevents FMRP production." (PMID 39975001, 2025). "It is important to note that several studies have reported reduced expression of mGluR5 in Fmr1 KO mice as well as in individuals with Fragile X Syndrome." (PMID 41177899, 2025). "Fragile X syndrome (FXS) is a neurodevelopmental disorder caused by the expansion of a CGG simple repeat in the 5’ untranslated region (5’UTR) of the fragile X messenger ribonucleoprotein 1 (FMR1) gene." (PMID 40287634, 2025). "Nonsense mutation in the highly conserved fmr1 gene, the silencing of which causes Fragile X syndrome (FXS) in humans, leads to decreased habituation toward visual stimuli in larvae, replicating a behavioral phenotype in human patients with FXS." (PMID 41323234, 2025). "Increased variability has been observed in the olfactory bulb of Shank3B−/− and Cntnap2−/− knock-out mice and the Fmr1 knock-out (KO) mouse model of fragile X syndrome." (PMID 41062277, 2025).
fragile X syndrome (continued). "Fragile X syndrome (FXS) results from loss of FMR1-encoded FMRP and is associated with reduced density of parvalbumin (PV) neurons; however, the mechanism underlying this abnormality remains unknown." (PMID 40672286, 2025). "The Fmr1 knock-out (KO) mouse model of fragile X syndrome (The Dutch-Belgian Fragile X Consortium, 1994) has deficits in learning to discriminate difficult novel odor mixtures compared with WT mice." (PMID 41062277, 2025). "Fragile X syndrome is a genetic disorder, caused by the expansion of a CGG trinucleotide repeat on 5′ UTR of the fragile X messenger ribonucleoprotein-1 (FMR1) gene." (PMID 40275386, 2025). "In Fragile X syndrome, expansion of CGG trinucleotides in the FMR1 gene and reduced FMRP protein are used as valid diagnostic biomarkers." (PMID 41465426, 2025). "Fragile X Syndrome (FXS), the most common inherited intellectual disability, is caused by CGG-repeat expansions in the FMR1 gene." (PMID 41386846, 2025). "In Fragile X Syndrome, the FMR1 gene is silenced due to an expansion of CGG repeats, a process regulated by DNA methylation and H3K9 methylation." (PMID 40469903, 2025). "In Down syndrome, increased interleukin-6 and SOD1; in Fragile X syndrome, elevated FMR1 mRNA and cytokine changes; and in Rett syndrome, increased ammonium and metabolic profile disturbances are observed." (PMID 41465426, 2025). "Similar repeat contractions in affected offspring have been reported in asymptomatic parents, typically fathers, with fragile X messenger ribonucleoprotein 1 (FMR1) CGG repeats in Fragile X syndrome." (PMID 40084170, 2025). "Fragile X syndrome is related to a number of CGG trinucleotide repeats >200 in the FMR1 gene’s promoter region." (PMID 40400398, 2025). "The Fragile X Mental Retardation 1 (FMR1) gene is well-known for its role in Fragile X syndrome, a neurodevelopmental disorder, but emerging evidence suggests its involvement in regulating cellular metabolism, with implications for cancer biology." (PMID 40563420, 2025). "In Fragile X syndrome (FXS), expanded (>200) CGG repeats trigger hypermethylation of the X-linked FMR1 promoter, resulting in gene silencing." (PMID 40228903, 2025). "DNA was directly analysed for the FMR1 CGG repeat expansion using repeat-prime PCR (indication under Fragile X syndrome) and a premutation of 110 CGG repeat units was confirmed." (PMID 39349043, 2025). "Fragile X syndrome (FXS) is the leading known genetic cause of autism, caused by a trinucleotide repeat expansion mutation in the 5′-untranslated region of the fragile X messenger ribonucleoprotein 1 (FMR1) gene located on the X-chromosome." (PMID 40190341, 2025). "In tune with our current results, previous studies showed a reduction of KCC2 protein expression in the hippocampus of VPA rats at P15 and P30 and the hippocampus of Fmr1-KO mice, model of Fragile X syndrome (FRX) (rare type of ASD) at P15 and P30." (PMID 40520207, 2025). "Fragile X Syndrome (FXS), caused by the loss of function of the Fmr1 gene, is characterized by varying degrees of intellectual disability, autistic features, and sensory hypersensitivity." (PMID 40995144, 2025). "Fragile X syndrome (FXS), typically caused by an expansion of the CGG triplet repeat (>200) in the fragile X messenger ribonucleoprotein 1 (FMR1) gene on Xq27.3, is the most common inherited form of intellectual disability, and the leading form of XLID." (PMID 41153441, 2025). "Fragile X syndrome (FXS), caused by a full mutation (>200 CGG repeats) in the gene Fragile X messenger ribonucleoprotein 1 (FMR1), is the most common single-gene cause of autism spectrum disorder (ASD)." (PMID 41346873, 2025). "CYFIP1 is used by the fragile X syndrome protein (FMRP), encoded by FMR1, to repress activity-dependent translation and has thus been linked with fragile X syndrome." (PMID 40176798, 2025). "Subsequently, his grandson was diagnosed with fragile X syndrome after detection of a full-range repeat expansion in FMR1." (PMID 39349043, 2025).
fragile X syndrome (continued). "Expansion of the CGG trinucleotide sequence within the 5′ UTR of the fragile X messenger ribonucleoprotein 1 (FMR1) gene is implicated in a spectrum of disorders, including fragile X syndrome (FXS) and the fragile X premutation–associated conditions (FXPAC)." (PMID 39320553, 2024). "FMRP/FMR1 is an RNA-binding protein related to fragile X syndrome and plays an influential role in regulating synaptic plasticity." (PMID 38785921, 2024). "While the full mutation (> 200 CGGs) is responsible for the fragile X syndrome (FXS), the leading single-gene cause of inherited intellectual disability, the FMR1 premutation (55–200 CGG repeats) has been associated, among others pathologies, with FXPOI." (PMID 38760837, 2024). "It has been shown that DGCR8 binds preferentially to expansion of CGG repeats in the 5′ UTR of FMR1 gene, thus showing a link between miRNAs regulation, Fragile X Syndrome, and vascular development." (PMID 39654947, 2024). "Fragile X syndrome (FXS) is a genetic disorder characterized by mutation in the FMR1 gene, leading to the absence or reduced levels of fragile X Messenger Ribonucleoprotein 1 (FMRP)." (PMID 38578387, 2024). "Social deficits have been reported in Fragile X syndrome, an ASD that is related to the mutation of FMR1 gene." (PMID 39056071, 2024). "The FMR1 gene, member of the fragile X-related gene family, is responsible for fragile X syndrome (FXS)." (PMID 38649916, 2024). "In addition, pharmacogenetics testing may be used to guide the selection of medications in ASD, a technique which is also used in Down syndrome, Fragile X syndrome (FMR1 gene), and the PTEN gene mutation, which encodes a phosphatase associated with extreme macrocephaly." (PMID 38672454, 2024). "Fragile X syndrome (FXS) is a neurodevelopmental disorder, caused by an CGG repeat expansion (FM, > 200 CGG) in the fragile X messenger ribonucleoprotein 1 (FMR1) gene." (PMID 39320553, 2024). "Fragile X syndrome (FXS) is a genetic form of intellectual disability and autism characterized by the inhibition of transcription of FMR1, the gene responsible for encoding the fragile X mental retardation (FMR) protein." (PMID 38474212, 2024). "Inactivation of the FMR1 gene results in fragile X mental retardation syndrome, while a duplication of FMR1 has been reported to be related with characterized such as short stature, hypogonadism and facial dysmorphism." (PMID 38383389, 2024). "In this study, we investigated ultrasonic vocalizations (USVs) and homing behavior in a mouse model of Fragile X Syndrome (FXS), a leading genetic cause of autism spectrum disorder (ASD) caused by a mutation of the X-chromosome linked Fmr1 gene." (PMID 38383408, 2024). "These genes include ATP Binding Cassette Subfamily B Member 1 (ABCB1) and Thrombospondin-1 (THBS1), as well as the fragile X messenger ribonucleoprotein 1 (FMR1) gene in Fragile X Syndrome to induce transcriptional repression." (PMID 39108836, 2024). "Epigenetic silencing of the FMR1 gene is the core pathological mechanism of Fragile X Syndrome (FXS), and its reversibility offers potential for treatment of FXS." (PMID 39220684, 2024). "The WES variant analysis is also insufficiently sensitive to the presence of simple tandem repeat expansions, such as in the FMR1 gene that are responsible for fragile X syndrome (MIM 300624), which have been found in many individuals with ASD." (PMID 38649688, 2024). "Fragile X syndrome (FXS) is a leading cause of autism spectrum disorder (ASD) and resulted from a loss of the FMR1-encoded fragile X messenger ribonucleoprotein 1 (FMRP) protein due to large CGG repeat expansions in the promoter region of the FMR1 gene." (PMID 37936174, 2023). "The features of the male gender, long face, cognitive impairment, and psychomotor delay suggested fragile X syndrome as the first provisional clinical diagnosis; however, FMR1-CGG repeats testing proved normal." (PMID 36780047, 2023).
fragile X syndrome (continued). "The same tool has been used in the context of fragile X syndrome (FXS), a disease characterized by a silencing of the FMR1 gene associated with hypermethylation of the CGG expanded repeats in the 5′UTR of FMR1." (PMID 36980849, 2023). "Disruption of the FMR1‐TAD boundary due to increased local methylation in the genome of Fragile X syndrome patients results in disrupted FMR1 interaction with telomere orientation cognate enhancers and decreased FMR1 expression." (PMID 37426677, 2023). "Early continuous inhibition of group 1 mGlu signaling partially rescued dendritic spine abnormalities in the Fmr1 knockout mouse model for fragile X syndrome." (PMID 36792602, 2023). "A long CGG repeat located in FMR-1 gene was involved in the phenotypic expression of the fragile X syndrome." (PMID 36768697, 2023). "For example, fragile X mental retardation (FMR1) KO mice, a model for the study of fragile X syndrome, have exaggerated mGluR‐LTD and increased STEP expression." (PMID 36971428, 2023). "Fragile X Syndrome (FXS) is caused by meiotic instability in the 5′ untranslated region of the X chromosome-linked Fragile X messenger ribonucleoprotein 1 gene (Fmr1), impeding the transcription of the Fragile X Messenger Ribonucleoprotein (FMRP)." (PMID 37323585, 2023). "The inactivation of the FMR1 gene results in fragile X syndrome (FXS), a serious neurodevelopmental disorder." (PMID 38003508, 2023). "Fragile X syndrome, an ASD-associated syndrome caused by mutations in the FMR1 gene, is a leading genetic cause of autism in humans." (PMID 37834345, 2023). "Fragile X syndrome (FXS) is the leading single-gene (Fmr1) cause of autism." (PMID 37691105, 2023). "For example, patients with fragile X syndrome typically carry >200 CGG repeats in the 5’ UTR of FMR1, while unaffected individuals generally have 6 to 53 repeats." (PMID 36380236, 2023). "A total of 108 women were referred to our center due to a related Fragile X syndrome (FXS) patient, 79 women carried a premutation of 56–199 repeats, and 19 women carried a full mutation of more than 200 CGG repeats on FMR1 gene." (PMID 37200782, 2023). "Previous studies have reported that MPEP decreased marble burying in normal mice, mice treated prenatally with valproic acid as a model for autism and FmR1 knockout mice generated as a model for fragile X syndrome." (PMID 37048075, 2023). "Mutation of FMR1, the gene encoding FMRP, causes Fragile X syndrome, another form of syndromic autism." (PMID 37545882, 2023). "Due to differential methylation between human and mouse genes, the Fmr1 KO is a widely used mouse model to study Fragile X Syndrome and is considered a better model than putative mimics of the CGG repeat expansion." (PMID 36909303, 2023). "A recent study showed that an acute and single intraperitoneal injection of SAHA in the mouse model of fragile X syndrome, Fmr1-KO, restores object location memory and passive avoidance memory and corrects repetitive behavior and social interaction deficits." (PMID 37759701, 2023). "In fragile X syndrome, both abnormally expanded CGG repeats and point mutations in FMR1 have been reported." (PMID 36380236, 2023). "Fragile X syndrome is caused by mutations in FMR1 gene (which encodes fragile X mental retardation protein, FMRP) expressed in both neurones and astrocytes." (PMID 37828019, 2023). "In this study, we developed an FMR1 KO iPSC-derived model to better understand how suppressing the expression of the FMR1 gene contributes to neurodevelopmental alterations that are observed in Fragile X syndrome." (PMID 37834379, 2023). "The D. m. genome contains the dFmr1 gene, which is homologous with the human FMR1 gene involved in neurodevelopmental Fragile X syndrome." (PMID 37239420, 2023). "In Fragile X Syndrome (FXS), an inherited type of autism, the loss of the fragile X mental retardation protein (FMRP, encoded by the X-linked FMR1 gene) results in excessive protein synthesis in neurons." (PMID 37047306, 2023).
fragile X syndrome (continued). "The FMR1 gene is inactive in Fragile X syndrome (FXS), resulting in low levels of FMRP and consequent neurochemical, synaptic, and local circuit neurophysiological alterations in the fmr1 KO mouse." (PMID 37162907, 2023). "These spines’ morphological defects on DAP-treated DCX+ cells are reminiscent of those observed on mature neurons from mutant mice of the fragile X mental retardation protein (Fmr1) and from human patients’ brains that suffer from the fragile X syndrome." (PMID 36720500, 2023). "Fragile X Syndrome (FXS) is rare genetic condition characterized by a repeat expansion (CGG) in the Fragile X messenger ribonucleoprotein 1 (FMR1) gene where individuals with greater than 200 repeats are defined as full mutation." (PMID 36816716, 2023). "Lack of FMR1 protein results in fragile X syndrome (FXS), which is the most common inherited intellectual disability syndrome and serves as an excellent model disease to study molecular mechanisms resulting in neuropsychiatric comorbidities." (PMID 36506088, 2022). "Fragile X syndrome (FXS) is the most common inherited form of intellectual disability and is caused by loss of function of the FMR1 gene that codes for the fragile X mental retardation protein (FMRP)." (PMID 35327449, 2022). "The overarching question highlighted in this review was how hyperexcitability emerges in Fragile X syndrome, focusing on physiological and molecular mechanisms uncovered in the Fmr1 knockout mouse model." (PMID 35682993, 2022). "Fragile X syndrome (FXS), caused by trinucleotide repeat expansions in the FMR1 gene in 99 percent of cases, is the most common single-gene cause of ASD." (PMID 35456390, 2022). "Fragile X syndrome, the major cause of inherited intellectual disability among men, is due to deficiency of the synaptic functional regulator FMR1 protein (FMRP), encoded by the FMRP translational regulator 1 (FMR1) gene." (PMID 35641906, 2022). "Fragile X syndrome (FXS) is considered as the leading monogenetic cause of autism, and the FXS phenotype could be well recapitulated in Fmr1 KO2 mice." (PMID 35309933, 2022). "In Fragile X syndrome, caused by a CGG repeat in the promoter of X-linked gene FMR1, it was DNA methylation and chromatin changes of the FMR1 repeated allele that was the mechanism for silencing of the repeated allele in males." (PMID 35356429, 2022). "Nucleotide repeats found in the FMR1 gene involved in Fragile X syndrome (d(CGG)n) have been shown to form G4 DNA, which can alter replication and transcription of the FMR1 gene." (PMID 40766048, 2022). "Fragile X syndrome (FXS) is caused by mutations in the FMR1 gene." (PMID 34791268, 2022). "Fragile X syndrome (FXS), which is the most common cause of inherited mental retardation, arises due to mutations occurring in the FMR1." (PMID 36142719, 2022). "Fragile X syndrome (FXS) is an X-linked genetic condition associated with an expansion of the trinucleotide (cytosine-guanine-guanine) CGG repeat within the 5′-untranslated region of the fragile X messenger ribonucleoprotein 1 (FMR1) gene." (PMID 36494616, 2022). "Mutations in FMR1, which encodes RNA binding protein FMRP, lead to fragile X syndrome: the most common cause of autism spectrum disorder." (PMID 35731217, 2022). "R-Loops have been found to form on expanded repeats in the FMR1 and FMX genes, known to be associated with Friedreich ataxia and Fragile X syndrome." (PMID 40766048, 2022). "As the fragile site symbol FRAXA has also confusingly been used in the literature to refer to the gene underlying “fragile X syndrome”, we also list “FRAXA” as an alias symbol for FMR1." (PMID 35741066, 2022). "FMR1 CGG repeat expansions into full mutations lead to cytosine methylation, epigenetic silencing of the allele and fragile X syndrome." (PMID 35641906, 2022). "Analogous changes, indicating general spine immaturity, were also shown in Fmr1 KO mice and patients with fragile X syndrome." (PMID 35505150, 2022).